MRC2 (mannose receptor C-type 2)
Diseases named in the same sentence as MRC2 in open-access papers (continued):
Sharing a sentence is not in itself a finding about the gene and the disease.
MRC2 also shares sentences with these, for which no sentence is quoted: fibrosarcoma (4 papers); mesothelioma (3); bone cancer (2); lung carcinoma (2); malignant mesothelioma (2); metastatic disease (2); myeloid leukemia (2); soft tissue sarcoma (2); synovial sarcoma (2); undifferentiated pleomorphic sarcoma (2); acute myeloid leukemia (1); acute promyelocytic leukemia (1); adenomyosis (1); anaplastic astrocytoma (1); anaplastic oligodendroglioma (1); benign prostatic hyperplasia (1); bone metastasis (1); cervical carcinoma (1); colorectal cancer (1); connective tissue disorder (1); COVID-19 (1); dwarfism (1); fibrosis (1); fibrous histiocytoma (1); giant cell tumor (1); Gliosis (1); gynecological disease (1); hypertrophic cardiomyopathy (1); invasive breast carcinoma (1); leiomyosarcoma (1).
A further 25 diseases each share a sentence with MRC2 in 1 paper.